INGX (inhibitor of growth family, X-linked (pseudogene))
Synonyms: ING1-like; formerly ING2
Gene: Transcribed processed pseudogene on chromosome X (71,492,083 to 71,492,928, reverse strand). Ensembl gene ENSG00000243468.
Diseases named in the same sentence as INGX in open-access papers:
INGX is named in the same sentence as 1 disease in open-access papers, as found by Europe PMC text mining. Sharing a sentence is not in itself a finding about the gene and the disease.
INGX shares sentences with these, for which no sentence is quoted: tumor (1 paper).